MIR449B (microRNA 449b)
Synonyms: hsa-mir-449b; MIRN449B; mir-449b
Gene: MicroRNA gene on chromosome 5 (55,170,646 to 55,170,742, reverse strand). Ensembl gene ENSG00000207728.
Pathways (Reactome):
Signal Transduction: Pre-NOTCH Transcription and Translation
Gene Ontology:
Biological process: miRNA-mediated post-transcriptional gene silencing
Homologues: Orthologues: chimpanzee ptr-mir-449b (100% identical), macaque mml-mir-449b (99% identical), dog MIR449B (90% identical), tropical clawed frog xtr-mir-449b (61% identical). Paralogues in human: MIR449A (48% identical).